ALB (albumin)
Diseases named in the same sentence as ALB in open-access papers (continued):
Sharing a sentence is not in itself a finding about the gene and the disease.
infection (continued). "However, exploratory analyses revealed a lower incidence of myocardial injury, and conversely higher bleeding-, re-sternotomy- and infection incidence in the albumin group compared with Ringers acetate." (PMID 38532434, 2024). "It is noteworthy that concomitant utilization of albumin after CRE colonization might be an effective measure to prevent the occurrence of CRE-colonized infection." (PMID 38659068, 2024). "Therefore, reduced albumin levels significantly reduce a patient’s resistance to infection and stress damage." (PMID 39699941, 2024). "Both CRL1505 and MPL16 were capable of significantly reducing S. pneumoniae lung colonization and the concentrations of BAL albumin as well as avoiding the pathogen’s dissemination the into the blood when infection was produced 1, 5, or 7 days after the treatment with lactobacilli." (PMID 39766307, 2024). "High values of RBC, hemoglobin, hematocrit, mean corpuscular hemoglobin (MCH), the albumin/globulin (A/G) ratio, and albumin and low levels of β-2 globulin and γ-globulin were found only in this canine breed, suggesting some resistance to infection in these dogs." (PMID 38891563, 2024). "In univariate analyses, variables associated with progression to infection included length of hospitalization, application of non-steroidal immunosuppressants, and serum albumin level." (PMID 38680915, 2024). "Univariate analysis showed that risk factors for developing infections were non-steroidal immunosuppressants, serum albumin levels, and days of hospitalization." (PMID 38680915, 2024). "Instead, non-steroidal immunosuppressants and albumin levels were identified as independent risk factors for the progression of infections." (PMID 38680915, 2024). "Furthermore, staple use showed similar outcomes to sutures in terms of albumin levels, pain scores, and superior prevention of surgical site infections." (PMID 39525136, 2024). "We found that albumin preexposure rendered R.delemar spores almost completely avirulent in vivo.Interestingly, pre-exposure to albumin did not inhibit the in vivogermination of Mucorales during the early stages of infection in the lungs." (PMID 39678331, 2024). "Furthermore, low albumin levels in patients with potential infectious foci can lead to infection recurrence." (PMID 38912203, 2024). "This suggests that certain biochemical profiles, particularly those involving ALB and GLOB ratios, may be inversely associated with the likelihood of infection." (PMID 39204236, 2024). "The differences between septic patients with and without DVT were studied from following aspects: basic information, comorbidities, inflammatory cytokines, albumin, source of infection, sequential organ failure assessment (SOFA) score, coagulation and prognosis." (PMID 38229151, 2024). "In addition, pregnant women who were inactive HBsAg carriers and those with active infection had significantly lower albumin, prealbumin, uric acid, and hemoglobin levels and platelet count." (PMID 36604811, 2023). "Serum albumin concentration is a possible early biomarker of microvascular changes, and thus indirectly of infection severity, which may make albumin an important prognostic element for infections." (PMID 37240554, 2023). "Additionally, albumin levels can be influenced by factors such as infection, liver function, fluid status and other comorbidities, extending beyond just nutritional status." (PMID 37810784, 2023). "Our study, based on a large cohort of patients admitted to the ED for an infection, suggests that using serum albumin values measured at admission together with the SOFA score may improve the prognostic assessment of these patients." (PMID 38137746, 2023). "In addition to nutritional status, serum albumin can be impacted by multiple factors, such as inflammation, immune function, infection, liver and kidney function, and chronic diseases." (PMID 37571238, 2023).
infection (continued). "Patients with infections who present in the ED with a low albumin level, particularly those who are hemodynamically stable, may be at a higher evolutionary risk of death." (PMID 38137746, 2023). "In the training group, univariate analysis showed that age, BMI, infection, ascites, urea, Na+, ALB, WBC, PLT, CTP score, MELD-Na score, CLIF-C ADs, IC, Z, K140, and ECVIC-liver were risk factors associated with the development of ACLF within 90 days in patients with HBV LC-AD (p < 0.05)." (PMID 36977956, 2023). "Hospital stays showed a strong association with occurrence of complication (rpb = 0.33, p < 0.00001), especially necrosis (rpb = 0.44, p < 0.00001), infection (rpb = 0.28, p = 0.00008), fistula (rpb = 0.30, p = 0.00003), and albumin levels (r = −0.21, p = 0.004)." (PMID 37629355, 2023). "All enrolled patients with infection were tested for serum albumin concentration." (PMID 37240554, 2023). "Note that decreased albumin is also an indicator of the infection status." (PMID 38014945, 2023). "The effects of CrCl and infection sites on clearance, body weight on volume of distribution in the central and peripheral compartments, albumin concentration and any infection site on the volume of distribution in the peripheral compartment were included in the final model." (PMID 37322293, 2023). "Moreover, elevated levels of CRP in conjunction with low albumin levels indicate a decline in albumin production and increased breakdown due to inflammation or infection." (PMID 38137581, 2023). "In addition, the performance of albumin has been investigated in patients with COVID-19 infection or other infections, consistently showing a direct correlation with a more severe infectious state." (PMID 38137746, 2023). "Additionally, albumin supplementation within 30 days after spinal surgery increased surgical-site infection rates." (PMID 36768655, 2023). "Moreover, 26.8% had low serum albumin, 19.2% an immunosuppression status, and 26.6% a clinical infection on admission." (PMID 36830131, 2023). "CCI, hemodialysis, previous infection, higher white blood cell count and creatinine, lower albumin, and vomit at presentation, higher creatinine increase from baseline, and higher Zar score were all associated with the occurrence of death in the univariate analysis." (PMID 37237740, 2023). "Indeed, a slight decrease in serum albumin significantly impacts hospital stay length, surgical site infections, and other health issues." (PMID 37809261, 2023). "An infusion of albumin decreased the level of PGE2, which may reduce the risk of infections in cirrhotic patients." (PMID 37218881, 2023). "Using a large cohort of patients who were admitted to the ED for an infection, the findings of this prospective study confirmed that the serum albumin concentration immediately recorded on ED admission is an independent risk factor for 30-day mortality (OR 3.767, 95% CI 2.192–6.437)." (PMID 37240554, 2023). "Whether an additional vaccine dose is needed should be determined based on antibody titers at 30 days, factors that maintain antibody titers, as well as indicators such as albumin and age, and the status of infection spread/reduction." (PMID 36376790, 2022). "Indicators such as white blood cell count, CRP, PCT, IL-6, and albumin may reflect the state of the body after infection to varying degrees." (PMID 36237437, 2022). "Serum albumin levels and transfemoral PCI approaches can be modified, and more restrictive use of diuretic medications, as well as frequent blood glucose monitoring, are warranted to minimize the risk of infection." (PMID 35497986, 2022). "Albumin concentrations fluctuate during inflammatory infections." (PMID 36501001, 2022). "Considering that the most abundant protein albumin in the serum may be affected by liver function, infection, nutrition, and many other factors, it was excluded from the verification list." (PMID 35910577, 2022).
infection (continued). "There were no between-group differences in the proportion of patients with indicators for severe infection, albumin < 3 g/dl, fever, history of gastrointestinal surgery within 30 days, history of antibiotic use over the past 30 days, transfer from other hospital." (PMID 35562785, 2022). "Oxygen saturation, hemoglobin levels, infection-related indicators, lymphocyte and platelet counts, C-reactive protein, serum albumin, liver and kidney function, and lactate dehydrogenase in improvement group were statistically significant between the improvement and death groups." (PMID 33762058, 2022). "Similarly, albumin concentrations greatly decreased by 9-day post-infection in chickens subjected to H. meleagridis infection, with normal levels of albumin and globulin fractions restored by 12-day post-infection, suggesting disease recovery." (PMID 35601402, 2022). "Male sex, ECOG PS > 1, non-IgA type MM and albumin ≤30 g/L allowed us to discriminate three subgroups of patients with different risk of early severe infection." (PMID 35440057, 2022). "And the serum levels of CRP and PCT increase apparently in response to infection or tissue injury, the degree of increase was significantly correlated with the severity of infection, and the ALB level may exist decrease during the response to acute infections." (PMID 35479953, 2022). "Specifically, B12, ROS, T.P and Albumin could play from the very early stages of the disease an important role as biomarkers as early indicators of the infection; while, other biochemical markers, such as ferritin and CRP increase as the disease progresses." (PMID 35736249, 2022). "Therefore, there have been studies regarding albumin as a single prognostic indicator in infections and as a combination indicator of albumin-based ratios." (PMID 36197158, 2022). "Compared with matched controls, patients with CRGNB infection had longer engraftment time of neutrophil (P=0.012) and platelet (P=0.002), lower albumin level in the early stages of infection (P=0.005), and worse prognosis (mortality rate 47.1% vs. 25.3%, P=0.005)." (PMID 36710978, 2022). "In addition to phosphorus, other factors have been identified to have a possible effect on serum/plasma zinc levels, such as time of day, albumin levels and infection." (PMID 35807763, 2022). "Patients in the experimental group showed significantly less decrease in body weight, serum albumin and haemoglobin levels, a lower incidence rates of grade ≥3 myelosuppression and infection, and a higher completion rate of CCRT than those in the control group." (PMID 35280748, 2022). "Additionally, this study linked the time from injury to operation < 10.5 days, preoperative albumin value < 38.5 g/L, and operation time > 84.5 minutes to postoperative incision infection." (PMID 36514037, 2022). "A low albumin level is a negative prognostic indication in hyperinflammatory conditions such as trauma, shock or infection and has been linked to poor outcomes and a shorter life expectancy." (PMID 35956107, 2022). "Both total protein and albumin are serum proteins produced by the liver that may be influenced by nutritional status and inflammation and infection." (PMID 36501001, 2022). "Therefore, dynamic monitoring of serum albumin is necessary and should be performed during treatment of patients with COVID, as a tool for assessing the prognosis of disease infections." (PMID 35736249, 2022). "Thus, taken with the significant decrease in MPO concentration, the reduction in albumin concentration for particle-treated mice suggests significant attenuation of lung injury during infection." (PMID 35737459, 2022). "In addition, increased immunoglobulin production during infection results in a dissociation between total protein and albumin." (PMID 35246574, 2022).
infection (continued). "The plasma ALB level might fall during the periods of stress, trauma, injury and infection, due to the redistribution from the intravascular to extravascular space, decreased synthesis and increased catabolism." (PMID 35572999, 2022). "Findings showed that ALB level was lower in MNg group compared with that in NNg patients, thus may result in more intra-abdominal fluid leakage, higher infection and incision complications." (PMID 35108317, 2022). "Therefore, patients need continuous infusion of albumin and immune enhancement to prevent infection." (PMID 35833031, 2022). "Upon multivariate analysis, an APACHE II score of ≥21, carriage of or infection with another MDRO, length of hospitalization, and serum albumin might be independent risk factors for fecal CRE colonization in our institution." (PMID 36445086, 2022). "In the LR model, the SOFA score was the most influential factor for prognostic prediction, and the top five risk factors were SOFA score, APACHE2 score, ICU hospitalization history within 3 months before infection, history of human albumin infusion within 3 months, and D-dimer level." (PMID 36445863, 2022). "An additional dysfunctional molecule of interest that could link the infection with severe syndrome is glycated albumin (GA)." (PMID 36235696, 2022). "Variables associated with increased risk of severe infection in the first 4 months included serum albumin ≤30 g/L, ECOG > 1, male sex, and non-IgA type MM." (PMID 35440057, 2022). "Recently, an increasing number of studies have demonstrated that serum GLO and the albumin to globulin ratio (AGR) present regularly vary in patients with infection, hepatitis, or tumors, indicating that they play a significant role in the immune and inflammatory systems." (PMID 35907808, 2022). "Probably, PC1 was associated with the factors responsible for the development of an infection process at 1 dpi, defining the lowered content of serums ALB, PHOS, and URA and immunoglobulins IgM, IgG1, and IgG2, as well as a decline in the egg production traits." (PMID 33535430, 2021). "The authors concluded that there was no significant loss of red blood cells or plasma albumin at the different levels of infection." (PMID 33669891, 2021). "Further studies are needed to determine whether the supplementation of albumin as coadjuvant treatment will have a positive impact on the prognosis of this infection." (PMID 34768653, 2021). "The protective effect of albumin was decreased when albumin was added 4 or 6 h after infection." (PMID 34154403, 2021). "Furthermore, the comparison of WT and hap5Δ transcriptional responses to infection in the presence of albumin demonstrates a failure to induce genes required for iron uptake, intracellular iron distribution and consumption in hap5Δ." (PMID 34710198, 2021). "However, infection with S. mansoni triggered a decrease in albumin, total protein and hemoglobin levels in LP 3% mice compared to control mice, and in all groups when compared to the levels observed before infection." (PMID 33815321, 2021). "A combination of the inflammatory response and increased capillary escape of albumin may also limit its oxidative influences in the interstitial space in infection, serious illness, and trauma, but at the same time provide substrate for tissue regeneration." (PMID 33925831, 2021). "The significant hyperproteinemia, consequent hyperglobulinemia, and decreased albumin/globulin ratio observed in pigeons following infection and/or exposure at 10 and 14 dpi/dpe was possibly due to increase in immunoglobulins in response to vvIBDV infection." (PMID 34150893, 2021). "During infection induced-hyperinflammation, serum albumin is reduced." (PMID 33640878, 2021). "Postoperatively, he was administered nasal continuous positive airway pressure-assisted ventilation, anti-infection treatment, albumin transfusion, platelet transfusion, abdominal drainage, methylprednisolone, fluconazole antifungal treatment, and wound dressing." (PMID 34918691, 2021).
infection (continued). "This leads us to entertain the hypothesis that increased catabolism of albumin is induced by infection related inflammation." (PMID 34768653, 2021). "Interestingly, ER stress induction prior to infection conferred resistance to C. glabrata-induced damage in the presence of albumin." (PMID 34710198, 2021). "Albumin negatively correlated with infection in patients with CLDs." (PMID 34571946, 2021). "In addition to higher SOFA score, older age, type-2 DM, lower serum albumin level and presentation of infection as a precipitating factor gave rise to significant higher risk of mortality over the long term." (PMID 33656122, 2021). "Furthermore, before infection, a significant reduction in albumin concentration was observed in LP 3% mice." (PMID 33815321, 2021). "The formal covariate analysis resulted in the identification of relationships between multiple subject descriptors (sex, infection status, serum albumin, and BSA) and rezafungin PK parameters that were statistically significant but not likely to be clinically significant." (PMID 34398673, 2021). "Previous studies have found that the rate of postoperative infection in orthopedic joint surgeries among HIV-positive patients was 23%, and CD4-CC < 300 cells/μl, hospitalization, multiple traumas, and low plasma albumin levels were all found to be associated with postoperative infections." (PMID 34616598, 2021). "Interestingly, E11 vRNA positive cells exclusively colocalized with albumin, identifying hepatocytes as the main cellular target of infection in the liver." (PMID 33513208, 2021). "In a first attempt, multiplicity of infection (MOIs) of 1, 2, 5 and 10 per vector were applied and cell supernatants were harvested at day 12 post-transduction (p.t.)for analysis of secreted porcine albumin by ELISA." (PMID 33927320, 2021). "ALB is an important protein for maintaining nutrition of the body and a normal nutritional status is an essential element for the immune system to fight against infection and inflammation." (PMID 35069542, 2021). "Also, under acute inflammatory conditions, albumin production in the liver is reduced (64, –, 66), with lower albumin levels correlating with the onset of infections and increased mortality in critically ill patients." (PMID 34154403, 2021). "However, the differential expression of these genes further underscores that iron homeostasis is crucial for albumin-augmented damage in our in vitro infection model." (PMID 34710198, 2021). "Therefore, an individual with lower albumin levels would be less prepared to respond against infection, leading to an exacerbation of the disease and an increased mortality." (PMID 34768653, 2021). "In addition, mice fed with the LP 3% diet showed a significant reduction in serum albumin levels in the period before infection and in all biochemical biomarkers assessed before perfusion." (PMID 33815321, 2021). "The body requires albumin and total protein to fight against infection and exert other functions; when their levels are lower than normal, liver damage or disease may occur." (PMID 33419092, 2021). "Moreover, during infection in the presence of albumin, C. glabrata drastically changed the expression of genes involved in iron uptake (FTR1 and SIT1), intracellular iron distribution and consumption (FTH1, HMX1) and virulence (EPA1, YPS2, AUS1)." (PMID 34710198, 2021). "In infection group children, lower vitamin E levels were associated with higher PRISMs (r = −0.238, P = 0.001) and CVSOFA (r= − 0.249, p < 0.001) scores, and associated with lower albumin and HB levels." (PMID 34222298, 2021). "We examined the association between albumin-corrected serum calcium level and risk of infection-related death by setting non-infection-related death as a competing risk." (PMID 32286455, 2020).